SIRT1 (sirtuin 1)
Diseases named in the same sentence as SIRT1 in open-access papers (continued):
Sharing a sentence is not in itself a finding about the gene and the disease.
diabetes (continued). "In diabetes, autophagy is negatively regulated by three nutrient-sensing pathways: mTORC1 activation, AMP-activated protein kinase (AMPK), and Sirtuin 1 (SIRT1) inhibition." (PMID 39941397, 2025). "Activates SIRT1 and AMPK; inhibits mTORC1 and tau aggregation, protecting against diabetes, CVD, and Alzheimer’s." (PMID 39858038, 2025). "A streptozotocin (STZ)-induced diabetes mellitus (DM) rat model was used to assess AF across four groups: sham, STZ, STZ with dapagliflozin, and STZ with dapagliflozin + sirtinol (a SIRT1 inhibitor)." (PMID 39636756, 2025). "In metabolic disorders, umbilical cord stem cell‐derived exosomes activate AMPK to facilitate muscle recovery in diabetes, while Lycium berry nanoparticles enhance muscle performance by elevating AMPK/SIRT1/PGC‐1α pathway activity." (PMID 41268687, 2025). "Sirtuin 1, a class III histone deacetylase, plays a critical role in the pathophysiology of both diabetes mellitus and bone metabolism by promoting osteoblast differentiation and inhibiting osteoclast maturation." (PMID 39944232, 2024). "At the molecular level, resistance exercise improves glycolipid metabolism and mitochondrial biogenesis through pathways such as the miR-30d-5p/SIRT1/PGC-1α axis, as evidenced by studies in type 2 diabetes mellitus (T2DM) models." (PMID 39769203, 2024). "By promoting the expression of the SIRT1 protein, SRT2104 mitigated diabetes-induced oxidative stress and endoplasmic reticulum stress in the testes, exerting a remarkable protective effect on testicular cells." (PMID 38448466, 2024). "Therefore, SIRT1 may play a role in DR by restoring SIRT1 protein expression in the kidneys, thereby improving autophagy dysregulation, counteracting inflammation, and alleviating renal damage in patients with diabetes." (PMID 39335456, 2024). "There is a functional link between SIRT1, with anti-inflammatory properties, and HMGB1 in the regulation of BRB breakdown induced by diabetes." (PMID 38716357, 2024). "It has been demonstrated that diabetes-induced inflammation strongly correlates with a reduced AMPK pathway, the downregulation of which leads to diminished SIRT1 activation." (PMID 37830574, 2023). "Another investigation using a rat model of streptozotocin-induced diabetes indicated that miR-93 targeted sirtuin 1 (SIRT1) in the diabetic retina, inducing changes indicative of oxidative stress and inflammation which could be reversed by SIRT1 overexpression." (PMID 37627644, 2023). "Metformin upregulates SIRT1 and AMPK to induce autophagy and thus improves severe complications of diabetes, including cardiac remodeling and heart failure." (PMID 37754811, 2023). "Yet, SIRT1, a diabetes-related gene that has been shown to enhance INS resistance and diabetes, is found to be higher in PDX1high/INShigh." (PMID 37270452, 2023). "The outcomes demonstrated that diabetes elevated miR-34a, p66Shc, CASP3, and PARP1 and downregulated let-7a-5p and SIRT1 expression." (PMID 38129872, 2023). "In diabetes, p66Shc expression and activity can be increased by pathways such as amyloid-beta accumulation, protein kinase c (PKC) isoform activation, and SIRT1 impairment." (PMID 38129872, 2023). "In the context of diabetes, the dysregulation characterized by heightened basal IGFBP-3 and diminished SIRT1 (Sirtuin 1) levels contributes to compromised corneal epithelial healing." (PMID 38276493, 2023). "Among these, major attention has been devoted to the diabetes-induced decreased expression of the NAD+-dependent histone deacetylase, Sirtuin 1 (SIRT1), as well as to changes in the physiological levels of specific, non-coding, single-stranded microRNAs." (PMID 36355510, 2022).
diabetes (continued). "For example, glycyrrhizin reduces diabetes-induced neuronal and vascular damage by inhibiting inflammation, specifically by activating HMGB1 through the sirtuin 1 (SIRT1) pathway." (PMID 35269741, 2022). "Based on text mining, most of the highly common diabetes-related genes in the literature were correlated with glucagon and AMPK signaling pathways such as HNF4A, PCK2, and SIRT1, which were among the most interactive genes in the PPI analysis." (PMID 36360783, 2022). "We examined the effect of CdCl2 exposure on FOXO1 expression due to the involvement of the FOXO proteins and sirtuin 1 (SIRT1) in glucose handling, development of diabetes, and potential role in the development of PDAC." (PMID 34905088, 2022). "Taken together, our data indicated that long-term aerobic exercise improves type 2 diabetes mellitus-related cognitive impairment by inhibiting JAK2/STAT3 and enhancing AMPK/SIRT1 pathways in mice." (PMID 35578689, 2022). "Previous studies have shown that overnutrition, such as diabetes, usually produces excessive NADH, and a decrease in NAD+ content often leads to a decrease in Sirt1 expression." (PMID 35090502, 2022). "SIRT1 activation by RSV leads to the deacetylation of both NF-κBp65 and H3, thereby attenuating cardiac oxidative stress and complications of diabetes." (PMID 35386302, 2022). "It was further reported that resveratrol treatment protected against the development of DKD by preventing a decrease in the expression of SIRT1, and these results were consistent with the results of studies in which STZ was used to induce diabetes in rats." (PMID 35277012, 2022). "The activation of SIRT-1 by RSV leads to deacetylation of both NF-κBp65 and H3, thereby attenuating cardiac oxidative stress and complications of diabetes." (PMID 35386302, 2022). "Accumulating evidence indicates that SIRT1 and SIRT6 are crucial players in chronic inflammation related to vascular homeostasis, cardiovascular disease, cardiac dysfunction and diabetes." (PMID 35328633, 2022). "Hyperglycemia-induced oxidative stress is involved in impaired SIRT1/Nrf2/HO-1 signaling and ischemia AKI in diabetes." (PMID 34063933, 2021). "It has been shown that the downregulation of sirtuin family members, such as SIRT1 and SIRT6, is closely related to the onset of insulin resistance and type 2 diabetes mellitus via inflammation and oxidative stress." (PMID 34073102, 2021). "Activation of SIRT1 led to deacetylation of FOXO1 and increased the transcriptional activity of FOXO1, ultimately enhanced the autophagy flux and protected diabetes-induced cardiac injury." (PMID 34367065, 2021). "SIRT1 activators like resveratrol, SRT1720 and MHY2233 can improve insulin resistance and have beneficial effects on diabetes- or obesity-induced fatty liver." (PMID 33809718, 2021). "Studies have also shown that SRT1720 plays an active role in the treatment of diabetes and insulin resistance, SRT1720 can promote wound healing and angiogenesis in diabetic mice in vivo and in vitro by activating SIRT1." (PMID 34616289, 2021). "However, our statistical analysis demonstrated that the sirtuin expression and oxidative stress parameters were not statistically different in the GCA patients with and without diabetes, confirming that SIRT1 expression is strictly linked to oxidative stress in GCA." (PMID 34073102, 2021). "Sirtuin-1 (SIRT1), a class III protein deacetylase, potentially plays a role in diabetes, inflammation, and neurodegeneration." (PMID 34239694, 2021). "Another study using high-fat diet and streptozotocin to induce diabetes and DKD in rats similarly found that metformin reduces oxidative stress and enhances autophagy in the kidney via AMPK/SIRT1-FoXO pathway." (PMID 33321755, 2020).
diabetes (continued). "In conclusion, by elevating the mitochondria-defender SIRT1 expression and at the same time decreasing the mitochondria-destroyer MMP9 expression in the diabetic eye, BGP-15 is able to counteract the retinal function-deteriorating effect of diabetes." (PMID 32204537, 2020). "AGEs can also promote insulin resistance and hence trigger diabetes by depleting the antioxidant defenses such as AGE receptor-1 and a survival factor sirtuin-1." (PMID 33085688, 2020). "Taken together, these results suggest that puerarin protects podocytes from diabetes-induced injury through HMOX1 and Sirt1-mediated upregulation of autophagy, a novel mechanism explaining its renal protective effects in DN." (PMID 32116781, 2020). "The expression and activity of Sirt1, Sirt2, Sirt3, and Sirt5 is reduced in a streptozotocin- (STZ-) induced type 1 diabetes mellitus (T1DM) model, while the level of Sirt3 is increased in a high-fructose diet-induced T2DM model." (PMID 32256959, 2020). "In this study, SIRT1 and SIRT3 expression was decreased in T1D and T2D, suggested their roles in the pathogenesis of diabetes." (PMID 30736780, 2019). "Previous studies have verified that SIRT1, an NAD+-dependent histone deacetylase, plays a positive role in type 2 diabetes mellitus (T2DM) with the function of anti-oxygenation and anti-inflammation." (PMID 30578379, 2019). "Taken together, our findings indicate that hyperglycemia-induced oxidative stress is involved in impaired SIRT1/Nrf2/HO-1 signaling and ischemia AKI in diabetes." (PMID 30578379, 2019). "SIRT1, a class III histone deacetylase downstream of AMPK36, is involved in many pathophysiological conditions, including diabetes and neurodegeneration." (PMID 30361632, 2018). "With type 1 diabetes a disease that is characterised by metabolic dysregulation, we sought to assess the impact of SIRT1 activation in experimental, streptozotocin (STZ)-induced diabetes." (PMID 30228292, 2018). "Sirt-1/AMPK pathway activation can reduce lipid accumulation in obese mice liver and improve insulin resistance in diabetes mice." (PMID 29563875, 2018). "In summary, administration of the SIRT1 activator, SRT3025, to mice with STZ-induced diabetes led to improved glycaemia with reductions in plasma glucagon and α cell hyperplasia without affecting either insulin secretion or ß-cell mass." (PMID 30228292, 2018). "The effect of the oral small molecule SIRT1 activator, SRT2104, on arterial stiffness was examined in otherwise healthy cigarette smokers and participants with type 2 diabetes mellitus." (PMID 27239324, 2016). "We further confirmed these results using ELISA which showed diabetes-induced increased ET-1 and TGF-β1 protein levels in the renal and retinal tissues are significantly reduced with SIRT1 overexpression in these tissues." (PMID 25753689, 2015). "To examine the downstream consequence of SIRT1 mediated alteration of ET-1 and TGF-β1 in diabetes, we investigated urinary micro-albumin levels to assess renal function in these mice." (PMID 25753689, 2015). "Resveratrol can promote Sirt1 expression by activating the AMPK pathway in 3T3-L1 cells and has the potential to improve insulin resistance in diabetes." (PMID 26413119, 2015). "We investigated the role of SIRT1 and its relationship with p300 in regulating ET-1 and TGF-β1 and their possible downstream consequences in ECs and tissues of animals affected by diabetes." (PMID 25753689, 2015).
diabetes (continued). "After adjustment for age, sex, diabetes mellitus, hypertension, cognitive status (MMSE scores), and number of co morbidities, serum SIRT1, SIRT2, and SIRT3 concentrations were found to be significantly lower in frail as compared to nonfrail patients." (PMID 25100619, 2014). "Since the level of AGE is elevated in the serum of patient with diabetes and Sirt1 expression in cultured podocytes is suppressed by AGE, we examined the expression of Sirt1 in the kidneys of patients with diabetes." (PMID 21858169, 2011). "Our study demonstrated that individuals suffering from diabetes exhibited lower SIRT1 concentrations compared with CKD patients without concomitant diabetes." (PMID 41009597, 2025). "These pleiotropic actions are primarily mediated through activation of AMP-activated protein kinase (AMPK) and sirtuin 1 (SIRT1), which are key regulators of cellular energy homeostasis and stress resistance, thus supporting the prevention and management of diabetes-related complications." (PMID 40807437, 2025). "In the present study, we examined the expression levels of NGF and Sirt1 in human pancreatic tissue specimens and found that they were lower in islet β cells in patients with diabetes than in those without and inversely correlated with insulin secretion." (PMID 41181709, 2025). "In this regard, overexpression of SIRT1 in mice fed a HFD increases browning and prevents diabetes." (PMID 40760244, 2025). "Sirtuin 1 represents another essential molecular link between OSA and diabetes." (PMID 41155523, 2025). "In our STZ-induced rat diabetes model, sirtinol reversed the glucose-lowering effect of DAPA, suggesting that SIRT1 inhibition may influence blood sugar levels." (PMID 39636756, 2025). "At baseline, there was a nonsignificant difference between the three groups regarding the age, gender, duration of diabetes, weight, height, BMI, FBG, 2 h-PPG, HbA1c%, TC, TG, HDL-C, LDL-C, non-HDL-C, VLDL-C, CRI, AI, and the inflammatory markers (hs-CRP, fetuin-A, and sirtuin 1) (p > 0.05)." (PMID 40481568, 2025). "In HF mice without diabetes, dapagliflozin, an inhibitor of sodium-glucose-linked transporter 2, decreased EndMT brought on by ISO via deacetylating and breaking down NICD by SIRT1." (PMID 41567643, 2025). "In the hearts of mice with streptozotocin-induced diabetes, as well as in rabbits with electrically induced atrial fibrillation, FF increased SIRT1 levels compared to model groups, but not above those of the sham-operated animals." (PMID 40869358, 2025). "Their regulatory effects on metabolism, inflammation, and immune responses are primarily mediated through signaling pathways, such as sirtuin 1 (Sirt1)/AMPK and PI3K/Akt/mTOR, contributing to their potential in the intervention of diabetes and cardiovascular diseases." (PMID 40978487, 2025). "In conclusion, ErL demonstrated anti-inflammaging influence in diabetes-associated periodontitis in vitro and it is proposed to be mediated through the CTBP1-AS2/miR-155/SIRT1 axis and, therefore, could be a potential therapeutic target in DM patients with periodontitis." (PMID 38396793, 2024). "However, another study showed that SIRT1 promotes insulin secretion and pancreatic beta cell survival by interacting with FOXO, which can alleviate diabetes." (PMID 38645427, 2024). "MiR-217/SIRT1 interaction has been revealed in a number of studies to contribute to the progression of age-related pathological/morbid conditions involving oxidative stress such as CVD, atherosclerosis, diabetes, neurodegenerative diseases and cancer." (PMID 38136977, 2023). "Left internal mammary arteries obtained from patients undergoing coronary artery bypass grafting with or without a diagnosis of diabetes were assayed for SIRT1 protein levels." (PMID 37401647, 2023). "The effects of AMPK and SIRT1 on metabolism raise the issue of whether SIRT1 and AMPK activating medications effectively change the fatty acid profile of diabetes patients under pathological settings." (PMID 37534224, 2023).
diabetes (continued). "In a diabetic environment, retinal epithelial cells expressed lower levels of MEG3 and SIRT1 and higher levels of miR-34a, meaning that diabetes could inhibit MEG3 and SIRT1 expression and increase miR-34a expression." (PMID 37762249, 2023). "FF prevents diabetes-induced cardiac dysfunction, inflammation, and cardiac remodeling and increases the expression of FGF21 and SIRT1 in both patients with and without diabetes." (PMID 37754811, 2023). "The enzyme Sirtuin 1 (SIRT1) which is a member of the sirtuin protein family is responsible for deacetylating the proteins critical for cellular regulation, and its gain of function increases energy efficiency and prevents diabetes in mice." (PMID 35132380, 2022). "Inactivation of Sirt1 by unhealthy diets was involved in the development and progression of NAFLD, diabetes, and metabolic syndrome, in which epigenetic modifications might play important roles." (PMID 36118762, 2022). "In addition, a SIRT1 activator with 1000-fold greater potency compared to resveratrol called SRT1720 has been synthesized and reported to be efficacious against type 2 diabetes mellitus and cancer in mice." (PMID 36225477, 2022). "In the diabetes model induced by a low-dose STZ injection (30 mg/kg) combined with a high-fat diet, the results of Western blotting showed that PPAR was significantly increased, whereas SIRT1 was significantly decreased, in the liver." (PMID 36295866, 2022). "The SIRT1 inhibitor also blunted the decrease in cardiomyocyte apoptosis after GDF11 overexpression, as well as the changes in apoptotic proteins induced by AAV-GDF11 in diabetes." (PMID 34262905, 2021). "Therefore, in this study, placental expression of FKBPL in conjunction with SIRT-1, PlGF and VEGF-R1 was investigated in human samples from pregnant women with pre-existing diabetes (T1D), and GDM." (PMID 34149611, 2021). "In conclusion, our study suggests that glycemic fluctuation in diabetes causes more damage in peri-implantitis compared with uncontrolled hyperglycemia, through regulating TLR2/4-IRAK1-TRAF6 pathway but not NAMPT/SIRT1 signaling." (PMID 34401982, 2021). "Dysregulation in FKBPL, SIRT-1, PlGF and VEGF-R1 demonstrated in this study, albeit with differential regulation in T1D or GDM, indicate the presence of angiogenic imbalance in pregnancies complicated by diabetes involving likely different mechanisms." (PMID 34149611, 2021). "The level of Klotho and SIRT1 in patients with combined diabetes and hypertension is not different with those with pure hypertension." (PMID 34670596, 2021). "FKBPL and SIRT-1 are critical regulators of angiogenesis, however, their roles in pregnancies affected by diabetes have not been examined before in detail." (PMID 34149611, 2021). "Furthermore, we investigated whether tested calystegines modulate the expression of SIRT1 transcription factors which is associated with glucose and lipid metabolism, however its role in the development of insulin resistance and diabetes is still not fully elucidated." (PMID 34034759, 2021). "miR-34a regulates diabetes-related protein cascades in the insulin signaling pathway, glucose metabolism, and cell proliferation through Akt, phosphatase 1 nuclear targeting subunit (PNUTS), and SIRT1 expression." (PMID 35052597, 2021). "Furthermore, sirtuin 1 (Sirt1) is a NAD+-regulated deacetylase and has been described to have protective effects in diabetes." (PMID 34502062, 2021). "Fascinatingly, SIRT1 together with AMPK are largely involved in the regulation of many cellular processes, including energy metabolism, cell cycle, insulin secretion, and apoptosis during the pathogenesis of diabetes." (PMID 32168855, 2020). "Sirtuin 1 (SIRT1), a NAD+-dependent deacetylase and important diabetes-related antioxidative gene, is critical in the regulation of cellular senescence, metabolic memory, apoptosis, glucose, and lipid metabolism, and influencing mitochondrial biogenesis, hypoxia, and angiogenesis." (PMID 32962281, 2020).